ATP5PD (ATP synthase peripheral stalk subunit d)
Description:
Subunit d, of the mitochondrial membrane ATP synthase complex (F(1)F(0) ATP synthase or Complex V) that produces ATP from ADP in the presence of a proton gradient across the membrane which is generated by electron transport complexes of the respiratory chain. ATP synthase complex consist of a soluble F(1) head domain - the catalytic core - and a membrane F(1) domain - the membrane proton channel. These two domains are linked by a central stalk rotating inside the F(1) region and a stationary peripheral stalk. During catalysis, ATP synthesis in the catalytic domain of F(1) is coupled via a rotary mechanism of the central stalk subunits to proton translocation (Probable). In vivo, can only synthesize ATP although its ATP hydrolase activity can be activated artificially in vitro (By similarity). Part of the complex F(0) domain. Part of the complex F(0) domain and the peripheric stalk, which acts as a stator to hold the catalytic alpha(3)beta(3) subcomplex and subunit a/ATP6 static relative to the rotary elements (By similarity).
Synonyms: ATP5H; ATPQ; ATP5JD; APT5H
Tractability: Small molecule: a structure with a bound ligand is known. PROTAC: ubiquitination databases record sites on it.
Gene: Protein-coding gene on chromosome 17 (75,038,855 to 75,047,718, reverse strand). Ensembl gene ENSG00000167863.
Subcellular location: Mitochondrion; Mitochondrion inner membrane
Subcellular location (Human Protein Atlas): Mitochondria
Pathways (Reactome):
Metabolism: Formation of ATP by chemiosmotic coupling
Metabolism of proteins: Mitochondrial protein degradation
Organelle biogenesis and maintenance: Cristae formation
Gene Ontology:
Molecular function: protein binding; proton-transporting ATP synthase activity, rotational mechanism; proton transmembrane transporter activity
Biological process: proton motive force-driven mitochondrial ATP synthesis; proton motive force-driven ATP synthesis; proton transmembrane transport
Cellular component: mitochondrial inner membrane; mitochondrion; proton-transporting ATP synthase complex
Genetic constraint (gnomAD): Loss-of-function variants: 13 observed, 23.67 expected, observed/expected ratio (o/e) 0.55, 90% interval 0.36 to 0.87. The upper end of that interval is the gene's LOEUF score, 0.87, which puts it in group 3 of 6, group 1 being the genes least tolerant of losing a copy. Missense variants: 165 observed, 196.37 expected, observed/expected ratio (o/e) 0.84, 90% interval 0.74 to 0.96. Synonymous variants: 51 observed, 68.06 expected, observed/expected ratio (o/e) 0.75, 90% interval 0.6 to 0.95.
Homologues: Orthologues: chimpanzee ATP5PD (100% identical), macaque ATP5PD (97% identical), guinea pig ATP5PD (88% identical), mouse Atp5pd (81% identical), rat Atp5pd (78% identical), zebrafish atp5pd (60% identical), tropical clawed frog atp5pd (57% identical), Drosophila melanogaster knon (35% identical), Caenorhabditis elegans atp-5 (24% identical).
Diseases named in the same sentence as ATP5PD in open-access papers:
ATP5PD is named in the same sentence as 20 diseases in open-access papers, as found by Europe PMC text mining. Sharing a sentence is not in itself a finding about the gene and the disease. The quoted sentences say what the papers report.
prion disease (1 paper, 2023). A transmissible disease that is caused by a protein that is able to induce abnormal folding of normal cellular proteins, leading to characteristic spongiform brain changes, which are associated with neuronal loss without an inflammatory response. "The genes predicted to be regulated in the “Prion disease” pathway by heroin-associated miRNAs included several transcription factors that have been demonstrated to regulate expression of proteins observed in our heroin-associated protein list, including Atp5pd (Elk1) and Uqcrfs1 (Elk1)." (PMID 38389822, 2023).
ATP5PD also shares sentences with these, for which no sentence is quoted: cancer (5 papers); tumor (3); Alzheimer disease (2); Parkinson disease (2); age (1); bipolar disorder (1); colon cancer (1); COVID-19 (1); glaucoma (1); Huntington disease (1); lung adenocarcinoma (1); mesothelioma (1); myoclonic dystonia (1); neurodevelopmental disorder (1); preeclampsia (1); primary immunodeficiency (1); renal oncocytomas (1); schizophrenia (1); small vessel stroke (1).